KEAP1 (kelch like ECH associated protein 1)
Diseases named in the same sentence as KEAP1 in open-access papers (continued):
Sharing a sentence is not in itself a finding about the gene and the disease.
lung carcinoma (continued). "To clarify the role of KEAP1 in the pathogenesis of lung cancer, we knock down of KEAP1 with two different short hairpin RNAs (shRNAs) in H1299, H23 and HCC827 cells." (PMID 38413563, 2024). "Conversely, some miRNAs, such as miR-200a in breast cancer, miR-432 in ESCC, and miR-421/miR-6077 in lung cancer, exhibit carcinogenic effects by negatively regulating KEAP1 mRNA levels, leading to resistance to different chemotherapeutic agents." (PMID 39061847, 2024). "NRF2 also promotes ferroptosis resistance by transcriptionally upregulating the expression of FSP1 in KEAP1-mutant lung cancers." (PMID 39624080, 2024). "Keap1-Nrf2 signaling pathway, as a typical antioxidant stress pathway, is abnormal in a variety of human malignant tumor diseases (such as lung cancer, liver cancer, and thyroid cancer)." (PMID 38634043, 2024). "KEAP1-mutant lung cancer is sensitive to GLUT1 inhibitors and suggests a potential therapeutic strategy to target disulfidptosis." (PMID 38910181, 2024). "KEAP1 was abundantly expressed in H1299 and H23 cells, while moderately expressed in other lung cancer cell lines." (PMID 38413563, 2024). "Initially discovered in lung cancer, gain-of-function mutations in NFE2L2 (the gene encoding NRF2) or loss-of-function mutations in KEAP1 were found to be frequently acquired by cancers, with a frequency of about 20% in lung adenocarcinoma (LUAD)." (PMID 39061847, 2024). "Consistent with the observations in human lung cancer cells, the overexpression of KEAP1 in LLC cells led to inhibited tumor growth and prolonged survival compared to the control cells." (PMID 38413563, 2024). "DRP-104 enhances immunotherapy responses in KEAP1 mutant lung cancer by suppressing T cell exhaustion and decreasing Tregs." (PMID 38536921, 2024). "To investigate the role of KEAP1 in lung cancer cells, we first determined KEAP1 protein levels in a panel of different lung cancer cell lines." (PMID 38413563, 2024). "Four lung cancer cell lines, A549, H1299, H460 and H358 showed robust PHGDH expression, and two of them, A549 and H460, in fact harbour a KEAP1 mutation." (PMID 38515202, 2024). "The frequency of co-mutations of KEAP1 and KRAS in lung cancers, which further increases treatment resistance and decreases survival, adds to the importance of addressing the biologic complexity and immune regulation by these tumors." (PMID 38542481, 2024). "To elucidate the clinical potential of KEAP1-mediated PD-L1 expression, we conducted IHC staining and analysis on tissue microarrays (TMAs) comprising lung cancer and corresponding adjacent normal tissues from non-small cell lung cancer (NSCLC) patients." (PMID 38413563, 2024). "We show that NMTis are effective as single agents against lung carcinomas with concurrent LKB1 and/or KEAP1 mutations in a KRAS-mutant background (KL/K)MUT and sensitize cells with these mutations to platinum-based chemotherapy." (PMID 38949950, 2024). "In summary, these findings strongly suggest that KEAP1 serves as a tumor suppressor, inhibiting lung cancer cell growth and colony formation." (PMID 38413563, 2024). "In this study, we found that the highly prevalent KEAP1 deficiency sensitizes NSCLC cells to AURKA inhibitors, establishing AURKA as a potential therapeutic target in specific lung cancer." (PMID 38521813, 2024). "KEAP1-mutant lung cancers decreased the recruitment of CD103+ dendritic cells and therein lowered CD8+ anti-tumor immunity." (PMID 38542481, 2024). "For example, co-mutation of KEAP1/STK11 was more common in patients with KRASG13-mutated lung cancer than in patients with KRASG12D-mutated lung cancer, and co-mutation of KEAP1/STK11 with KRASG13 was associated with poor prognosis and treatment resistance." (PMID 38310130, 2024).
lung carcinoma (continued). "We report that NMTs are a novel therapeutic target in lung carcinoma cells with LKB1 and/or KEAP1 mutations in a KRAS-mutant background." (PMID 38949950, 2024). "KRAS-mutant lung carcinomas with LKB1 and/or KEAP1 co-mutations have intrinsic therapeutic resistance." (PMID 38949950, 2024). "Knockout (KO) of FSP1 strongly sensitizes KEAP1 mutant lung cancer cells to ferroptosis and shRNA-depletion of FSP1 is sufficient to suppress tumor growth in a KEAP1-deficient lung cancer xenograft model." (PMID 38908072, 2024). "Our preclinical findings provide compelling evidence that DRP-104, currently in clinical trials, offers a promising therapeutic approach for treating patients with KEAP1 mutant lung cancer." (PMID 38536921, 2024). "Blocking the CoQ-FSP1 axis renders KEAP1-mutant lung cancer cells more vulnerable to radiation therapy by triggering ferroptosis, indicating FSP1 as a promising therapeutic target for combating treatment resistance in these malignancies." (PMID 39944353, 2024). "This explains why these NADPH-producing enzymes are selected as targets by NRF2 and are markedly elevated in KEAP1 mutant lung cancers." (PMID 38206305, 2024). "A recent study by UT MD Anderson Cancer Center found that when KEAP1, SMARCA4, and CDKN2A co-mutate with KRAS-G12C, KRASG12Ci monotherapy is ineffective in treating patients with advanced lung cancer." (PMID 38817907, 2024). "As a result, the SUMOylation of KEAP1 promoted the growth of H1299 lung cancer cells to promote tumor progression in this study." (PMID 37660919, 2023). "The Oncoprint of the cohort contains select alterations of functional significance, including lung cancer driver genes KEAP1/NFE2L2 and DDR pathway genes." (PMID 36602799, 2023). "Consistent with this, chromatin immunoprecipitation assays revealed higher NRF2 binding to the promoter regions of antioxidant genes in cells expressing the KEAP1-WT compared to the KEAP1-K39R mutant protein in H1299 lung cancer cell." (PMID 37660919, 2023). "SCD1 inhibition induces ferroptosis in STK11/KEAP1-comutated lung cancer cells and blocks tumor growth." (PMID 37047797, 2023). "One study reports the overexpression of Keap1/Nrf2 without reaching a significantly worse survival rate, while in lung cancer it was found that Keap1/Nrf2 is an independent prognostic factor." (PMID 37894373, 2023). "This study not only establishes CoQ-FSP1 as a new downstream effector of the KEAP1-NRF2 pathway but also provides an additional therapeutic target for treating KEAP1-mutant lung cancer." (PMID 36632216, 2023). "At the same time, the combination of them can also target Nrf2/Keap1 to regulate the drug sensitivity of lung cancer cells." (PMID 37005430, 2023). "The significance of this suppression of KEAP1 activity by its SUMOylation was tested in a subcutaneous tumor model of H1299 lung cancer cell lines that differentially expressed the WT and K39R KEAP1 constructs." (PMID 37660919, 2023). "Targeting the CoQ–FSP1 axis is a promising approach to sensitize KEAP1-mutant lung cancer cells or tumors to radiation therapy by inducing ferroptosis." (PMID 37371948, 2023). "SUMOylation of the endogenous levels of KEAP1 was demonstrated by immunoblotting peptides, which were enriched with an anti-KEAP1 antibody from human H1299 lung carcinoma cells untreated or treated with 2-D08, with an anti-SUMO1 antibody." (PMID 37660919, 2023).
lung carcinoma (continued). "For instance, Kelch-like ECH-associated protein 1 (KEAP1) mediates EMSY degradation, leading to enhanced homologous recombination and PARPi resistance in lung cancer." (PMID 36694209, 2023). "The glutaminase inhibitor CB-839 has been shown to produce an anti-tumor effect in KRAS-mutant lung cancer cells which carry inactivation of the KEAP1 gene resulting in NRF2 hyperactivation and xCT overexpression." (PMID 36338517, 2022). "We further show that targeting the CoQ-FSP1 axis sensitizes KEAP1 mutant lung cancer cells or tumors to radiation by inducing ferroptosis, thereby identifying a novel therapeutic strategy to target ferroptosis in KEAP1 mutant lung cancers." (PMID 35459868, 2022). "Herein, bioinformatic analysis suggests bromodomain-containing protein 4 (BRD4) as a potential top transcriptional regulator of KEAP1 in lung cancer." (PMID 35453346, 2022). "We identified BRD4 as a potential factor positively modulating KEAP1 expression at the transcriptional level in lung cancer." (PMID 35453346, 2022). "We used the A549 lung cancer cell line to verify that HSP90 regulation on COX2 requires active Keap1." (PMID 35362892, 2022). "We obtained similar results by treating iFSP1 in several KEAP1 mutant lung cancer cell lines (A549, H460, and H2126 cells)." (PMID 35459868, 2022). "We confirmed that KEAP1 deletion markedly increased levels of NRF2 and its transcriptional target SLC7A1138 in H1299 cells (a KEAP1 wild-type [WT] lung cancer cell line), and correspondingly rendered H1299 cells resistant to ferroptosis induced by erastin." (PMID 35459868, 2022). "This suggests an effective therapy for lung cancer patients with wide-type KEAP1 through combined treatment of glutaminase inhibition and NEAA deprivation." (PMID 35178349, 2022). "Experimentally, FSP1 deletion markedly repressed tumor growth of KEAP1-KO lung cancer cells in a xenograft model, suggesting that FSP1 is required for KEAP1-deficient lung tumor growth." (PMID 36264074, 2022). "After knockout of KEAP1 in lung cancer cells, the authors found upregulation of NRF2 and SLC7A11 expectedly, but the GPX4 level even decreased in these lung cancer cell lines." (PMID 36264074, 2022). "Further analyses revealed that FSP1 expression is significantly upregulated in KEAP1 mutant lung cancers (including both LUADs and LUSCs) compared with KEAP1 WT cancers." (PMID 35459868, 2022). "Pearson correlation analysis was performed to assess the correlation between the 23 potential transcription factors and KEAP1 expression in lung cancer." (PMID 35453346, 2022). "In a lung cancer model, lung-specific K-ras expression and Keap1 deletion worsened the survival of mice; however, attenuation of Keap1 expression in immune cells improved survival." (PMID 35053572, 2022). "Collectively, our data suggest using of 4-CBA to overcome radioresistance in KEAP1 inactivated lung cancers." (PMID 35459868, 2022). "KEAP1 (kelch-like ECH associated protein 1) is frequently mutated or inactivated in lung cancers, and KEAP1 mutant lung cancers are refractory to most therapies, including radiotherapy." (PMID 35459868, 2022). "ChIP analyses revealed strong NRF2 binding on both AREs in A549 cells (a KEAP1 mutant lung cancer cell line)." (PMID 35459868, 2022). "Together, our study identifies CoQ-FSP1 as a key downstream effector of KEAP1-NRF2 pathway and as a potential therapeutic target for treating KEAP1 mutant lung cancers." (PMID 35459868, 2022). "In lung cancer cells, it was shown that glutaminase inhibition can sensitize the radiation-induced treatment resistance in the Keap1 and Nrf2 mutant cells." (PMID 35945195, 2022).
lung carcinoma (continued). "In this review, we will describe the molecular mechanism regulating this signaling pathway in physiological conditions and summarize the most important findings related to the role of NRF2/KEAP1 in lung cancer." (PMID 34440648, 2021). "Recent PDX treatment shows good response for GLUT inhibitors for lung cancer PDX models (IDs: TC333, TC453, and TC494) carrying KEAP1 or NFE2L2 mutations." (PMID 34429404, 2021). "Our previous study showed that overexpression of Nrf2 due to Keap1 mutation increased cell invasion and metastatic ability of EGFR tyrosine kinase inhibitor (TKI)-resistant lung cancer cells both in vitro and in vivo." (PMID 33441941, 2021). "Four samples contained both KEAP1 and STK11 mutations, which have been shown to indicate lung cancer patients." (PMID 34830758, 2021). "Previous research had confirmed the effect of methylation on KEAP1 transcription control across multiple histologies of lung cancer." (PMID 34247575, 2021). "NRF2 is over-activated in lung cancer either through mutations of the NRF2 encoding gene, NFE2L2, or loss-of-function mutations of KEAP1, whose protein product ubiquitinates and degrades NRF2." (PMID 34344431, 2021). "In a Keap1-wt xenograft model of lung cancer, using the Nrf2 inducer bardoxolone triggered an increase in NRF2 expression and reduced the number of lung metastases." (PMID 34440648, 2021). "Taken together, these studies provide evidence that the release of NRF2 from KEAP1 is important for the survival and the proliferation of lung cancer." (PMID 34566633, 2021). "Keap1 is expected to serve as a potential tumor marker to guide the staging and treatment of lung cancer." (PMID 34466284, 2021). "LKB1-inactivated KRAS mutant lung cancers harbor co-mutations in KEAP1 and/or significant co-occurrences of copy number loss in STK11/LKB1 and KEAP1 due to the chromosomal proximity of these genes." (PMID 34680229, 2021). "CB promotes the poly-ubiquitination of NRF2 by β-TrCP, which in turn suppresses the growth of KEAP1 mutant NSCLC lung cancer xenografts." (PMID 34440648, 2021). "Here, we found a stable 105 kDa Nrf2 form that is resistant to Keap1-Cul3-mediated degradation and translocates to the nucleus of lung cancer cells." (PMID 34063559, 2021). "Taken together, these data suggest that a subset of the KEAP1 mutations leads to elevate SOX9 protein level, which is associated with lung cancer progression." (PMID 33173725, 2020). "It has been reported that KEAP1 mutations lead to the overexpression of NRF2 and its downstream genes in lung cancer." (PMID 32327612, 2020). "KEAP1/NRF2 mutant lung cancer is a microenvironmentally distinct, biologically heterogeneous and clinically underestimated disease that increased radioresistance in NSCLC." (PMID 33186371, 2020). "Compared with A549 lung cancer cell lines trasfected with WT KEAP1, proliferation of the A549 lung cancer cell line trasfected with the R320Q KEAP1 mutant was dramatically inhibited by ML385." (PMID 32576270, 2020). "Epigenetic deregulation has been increasingly recognized as one of the major mechanisms of the KEAP1 gene deregulation in lung cancer." (PMID 32971994, 2020). "For example, in lung cancer, CDK20 was reported involved in the in radio-chemotherapy resistance by interacting with the Kelch-like ECH-associated protein 1 (KEAP1)–nuclear factor erythroid-2-related factor 2 (NRF2) pathway." (PMID 33198081, 2020). "KEAP1/NRF2 signalling regulates glutaminolysis metabolism by inhibition of glutaminase in KRAS-KEAP1 mutant lung cancer and regulates the sensitivity to EGFR-TKI." (PMID 33186371, 2020). "Keap1-mutant lung cancer cells have been shown to demonstrate increased sensitivity to GLS inhibition and glutamine deprivation." (PMID 32937954, 2020).
lung carcinoma (continued). "In another example, an intergenic C > G mutation 2166 bp from the 3′-UTR of NFE2L2 in a lung cancer case leads to a new junction that pairs with a site embedded in the start of the last exon of NFE2L2, potentially disrupting NFE2L2/KEAP1 interaction." (PMID 33149122, 2020). "The expression levels of HO-1 and NRF2 protein in A549 lung cancer cells transfected with F174L, R234W, R320Q, and R413L KEAP1 mutants were significantly inhibited by ML385." (PMID 32576270, 2020). "Loss-of-function type mutation in KEAP1 results in activation of NRF2, which accelerates lung cancer cell growth." (PMID 32723974, 2020). "The discovery of KEAP1 promoter hypermethylation, leading to gene silencing in lung cancer, prompted widespread research on epigenetic regulation of the NRF2 signaling pathway." (PMID 32938017, 2020). "Therefore, we aimed to test whether mutations in KEAP1, identified in our previous study, accelerate the development of lung cancer, and whether a NRF2 inhibitor can be used as a targeted therapeutic drug in patients with lung cancer carrying KEAP1/NRF2 mutations." (PMID 32576270, 2020). "Thus, we checked whether KEAP1 loss could decrease ROS production in lung cancer cell lines." (PMID 32576270, 2020). "The lung cancer cell line A549 transfected with the R320Q KEAP1 mutant (KEAP1-R320Q mutant) or with WT KEAP1 (KEAP1-WT) and H1299 lung cancer cells, which carry both WT KEAP1 and NRF2, were selected and treated with ML385." (PMID 32576270, 2020). "Collectively, these results indicate that aberrant activation of NRF2 in KEAP1 mutant lung cancer cells confers resistance to β-lapachone exposure." (PMID 32007910, 2020). "Taken together, these results strongly suggest that β-catenin stimulates miR-421 expression, which in turn downregulates KEAP1 expression in lung cancer." (PMID 31659154, 2019). "Dysregulation of KEAP/NRF2 pathway due to loss of function mutations in the KEAP1 gene as well as gain-of-function mutations in NRF2 and epigenetic changes leads to drug- and radio-resistance in lung cancer." (PMID 31839815, 2019). "KEAP1, NFE2L2, and CUL3 are responsible for dysregulation of oxidative stress pathway in lung cancer and they have been shown to have elevated mutation rates in NSCLC." (PMID 30992440, 2019). "We performed a detailed methylation density map of 13 CpGs located into the KEAP1 promoter region by analyzing a set of 25 cell lines from different histologies of lung cancer." (PMID 31159323, 2019). "Our results confirm the effect of methylation on KEAP1 transcription control across multiple histologies of lung cancer." (PMID 31159323, 2019). "This analysis opens the debate on how many and which CpG sites of the KEAP1 promoter should be analyzed to set a clinical cut-off in lung cancer affected patients." (PMID 31159323, 2019). "An elegant study has demonstrated that dysregulation of the NRF2/KEAP1 system can impact lung cancer survival by increasing the metastatic potential of lung cancer cells." (PMID 35582567, 2019). "To discover a small‐molecule Keap1/Nrf2 pathway inhibitor, we conducted high‐throughput screening in Keap1 mutant human lung cancer A549 cells using a transcriptional reporter assay." (PMID 30735010, 2019). "Along with a more recent report finding GLUT8 as a vulnerability in KRAS/KEAP1 mutant lung cancer cell lines, these results suggest metabolic vulnerabilities exist within Redox54." (PMID 31395880, 2019). "An in vivo study in mice xenotransplanted with A549 cells to further explore the therapeutic potential of K‐563 revealed that it also inhibited Keap1/Nrf2 pathway in lung cancer tumors." (PMID 30735010, 2019). "The key finding of our study is that miR-421 is involved in the modulation of KEAP1 and the downregulation of KEAP1 expression by directly targeting the KEAP1 3′UTR in lung cancer." (PMID 31659154, 2019).